MEG3 (maternally expressed 3)
Diseases named in the same sentence as MEG3 in open-access papers (continued):
Sharing a sentence is not in itself a finding about the gene and the disease.
glioma (continued). "Other researchers have found the expression of lncRNA MEG3 is significantly down-regulated in glioma tissues and cells, and its overexpression can significantly inhibit cell proliferation and promote apoptosis and autophagy of glioma cells." (PMID 33614483, 2020). "In view of cells that have undergone EMT, namely, acquiring resistance to senescence and even to apoptosis, the suppression of MEG3 on EMT indicates the protective role of MEG3 in glioma cells by promoting cell apoptosis of tumor cells." (PMID 32420340, 2020). "To conclude, this study recognizes lncRNA MEG3 as a tumor inhibitor and a potential therapeutic biomarker for glioma." (PMID 32420340, 2020). "MEG3 promoted glioma cell autophagy and inhibited cell proliferation and migration through positively regulating Sirt7 by inhibition of the PI3K/AKT/mTOR signaling pathway." (PMID 33061817, 2020). "As a tumour suppressor gene, lncRNA MEG3 is the focus of tumour investigations and can inhibit the proliferation and metastasis of various tumour cells, including breast, lung, glioma, cervical, gastric and liver cancer cells." (PMID 32436312, 2020). "Although these results were solid evidence to support the tumor suppressor role of MEG3 in glioma, the specific mechanism, however, is far from being illustrated." (PMID 32420340, 2020). "lncRNA MEG3 was found to be markedly downregulated in glioma tissues and cell lines, which is an independent biomarker of poor prognosis in glioma." (PMID 33029125, 2020). "In our finding, we assured that MEG3 blocked the proliferation, invasion, and migration of glioma cells, which was in line with previously published data." (PMID 32420340, 2020). "Compared with normal brain tissue, MEG3 was found to be downregulated in glioma and glioblastoma cell lines and overexpression of MEG3 leads to increased cell death and inhibition of cell proliferation." (PMID 32283739, 2020). "This work is designed to explore the effect of MEG3 on glioma progression and its possible mechanism." (PMID 32420340, 2020). "Collectively, the evidence in this study indicated that MEG3 was downregulated in glioma cells and inhibited proliferation and migration of glioma cells via regulating miR-6088/SMARCB1 axis." (PMID 32420340, 2020). "Altogether, these findings indicate that the overexpression of MEG3 can inhibit glioma cell progression, while the overexpression of miR-6088 or the inhibition of SMARCB1 can partially reverse the inhibitive effect of pcDNA3.1-MEG3 on glioma cells." (PMID 32420340, 2020). "A MEG3 gene transcribes a 1.6 kb lncRNA, which acts as an antitumor component in different cancer cells, such as breast, liver, glioma, colorectal, cervical, gastric, lung, and ovarian and osteosarcoma cancer cells." (PMID 33299646, 2020). "In human glioma cells, upregulation of MEG3 inhibited cell proliferation while increasing cell apoptosis and autophagy." (PMID 33061817, 2020). "MEG3 was a widely researched lncRNA in neoplasms, including osteosarcoma, glioma, gallbladder cancer, and breast cancer." (PMID 32065781, 2020). "Herein, we can draw a conclusion that MEG3 regulates cell growth of glioma cells through mediating the miR-6088/SMARCB1 axis." (PMID 32420340, 2020). "piRNA-DQ593109/ PIWIL1 in glioma endothelial cells increased blood-tumor barrier (BTB) permeability by binding to maternally expressed 3(MEG3) lncRNA of the MEG3/miR-330-5p/RUNX3 axis." (PMID 31399034, 2019). "Recently, one study illustrated that the down‐regulation of MEG3 expression in glioma is due to hypermethylation of its promoter." (PMID 30117678, 2018).
glioma (continued). "For instance, lncRNA MEG3 promotes the proliferation of glioma cells through targeting Wnt/β-catenin signal pathway;38 lncRNA PLIN2 promotes the development of chronic myelogenous leukemia via the GSK3 and Wnt/β-catenin signaling pathways." (PMID 30166525, 2018). "lncRNA MEG3 was downregulated in a variety of primary cancers and found to be a prognostic factor for patients with glioma." (PMID 30069164, 2018). "Elevated MEG3 enhanced the chemosensitivity of glioma cells to cisplatin through eliminating autophagy induced by cisplatin." (PMID 30266744, 2018). "For example, lncRNA MEG3 inhibited miR‐93 level and the expression of PI3K/AKT pathway related proteins, forming the MEG3‐miR‐93‐PI3K‐AKT pathway in glioma cells." (PMID 30270508, 2018). "MEG3 is a tumor suppressor lncRNA gene, its expression is decreased in multiple tumors including lung cancer, gastric cancer, hepatocellular carcinoma, glioma etc.." (PMID 30026672, 2018). "Overexpression of MEG3 in human glioma cell lines inhibits cell proliferation and promotes cell apoptosis." (PMID 29138748, 2017). "MEG3 is abnormally expressed in various human cancers, such as hepatocellular carcinoma, bladder cancer, glioma, gastric cancer and CRC." (PMID 28108736, 2017). "Meanwhile, EZH2 was shown to suppress lncRNA SPRY4-IT1 expression in the NSCLC cells, and DNMT1-mediated DNA methylation was found to lead to MEG3 silencing in gliomas." (PMID 28209205, 2017). "Expression of the tumor suppressor lncRNA MEG3 is markedly decreased in glioma tissues and its ectopic expression inhibits proliferation and promotes apoptosis in human glioma cell lines." (PMID 28423669, 2017). "For example, lncRNA GAS5 can function as a ceRNA for miR-21; long non-coding RNA H19 promotes glioma cell invasion by deriving miR-675; Long non-coding RNA MEG3 functions as a competing endogenous RNA of miR-181 s to regulate gastric cancer progression." (PMID 27620004, 2016). "One such lncRNA, Maternally Expressed Gene 3 (MEG3), demonstrates markedly decreased expression in glioma, gastric cancer and non-small cell lung cancer tissues compared with adjacent normal tissues." (PMID 27733185, 2016). "Among those, levels of the lncRNA MEG3 are markedly lower in glioma tissues than adjacent normal tissues, and ectopic expression of MEG3 inhibits cell proliferation and promotes apoptosis." (PMID 26305674, 2015). "Taken together, the potential implication of MEG3 as a therapeutic target in the treatment of glioma is considerable." (PMID 26230711, 2015). "The maternally expressed gene 3 (MEG3) lncRNA has also been correlated with gliomas, but in contrast to H19, the MEG3 levels are markedly decreased in gliomas, while its overexpression inhibits cell proliferation and promotes apoptosis in vitro." (PMID 25654223, 2015). "MEG3, an lncRNA with tumor-suppressive functions, displayed significant downregulation in glioma tissue samples when compared with adjacent normal tissues and its overexpression in two GBM cell lines promoted apoptosis." (PMID 26287251, 2015). "MEG3 overexpression has been shown to promote cell apoptosis in glioma cell lines and inhibit cell proliferation in glioma and meningioma cell lines." (PMID 25559585, 2015). "For example, we found three SNPs (rs141600967, rs111946796, rs147394431) in the TFBSs of a lincRNA, ENSG00000214548 (also known as MEG3), ENSG00000214548 has been demonstrated to be associated with multiple human diseases, including glioma and neuroblastoma." (PMID 25075616, 2014).
glioma (continued). "Ectopic expression of MEG3 inhibits cell proliferation and induced cell apoptosis in glioma cell lines." (PMID 24550934, 2014). "MEG3 represents as a tumor suppressor gene, and its ectopic expression can inhibit cell proliferation and promote cell apoptosis in human glioma cell lines." (PMID 24098911, 2013). "Previously, it was shown that immune cell markers in tumor infiltrating immune cells including NK cells negatively correlated with the level expression of MEG3 in glioma microenvironment suggesting that MEG3 plays an important role in immune escape in the glioma microenvironment." (PMID 40781182, 2025). "Therefore, an association exists between DNMT1 and MEG3 promoter methylation, wherein DNMT1 showcased an inverse relationship with MEG3 expression in gliomas." (PMID 40387409, 2025). "Moreover, the upregulation of MEG3 was found to effectively suppress the proliferation, migration, and invasion of glioma cells." (PMID 39553554, 2024). "Moreover, MEG3 was found to suppress the miR-96-5p expression in glioma cells, whose expression levels were tied to glioma tissues and cells." (PMID 39553554, 2024). "The most prominent role of MEG3 in glioma is cell cycle regulation." (PMID 37525401, 2023). "Despite various studies indicating that the loss of MEG3 expression was detected in various cancer types including glioma, here we report that different glioma cells may be affected differently by MEG3 expression and MEG3 manipulation." (PMID 37525401, 2023). "The expression of MEG3 in many primary human tumors is significantly lower than that in normal adjacent tissues, including neuroblastomas, lung cancers, liver cancers, gliomas, prostate cancers, and colon cancers." (PMID 36851033, 2023). "U87MG glioma cells showed reduced cell proliferation when MEG3 was silenced." (PMID 37525401, 2023). "The effects of MEG3 silencing on HUVEC cells were almost the same as it was on glioma cells." (PMID 37525401, 2023). "In addition, EZH2 increases miR-21 levels in glioma cells by epigenetically inhibiting the expression of a long non-coding RNA called MEG3." (PMID 36829176, 2023). "This study aims to discover the role of MEG3 in glioma cells and to investigate how MEG3 affects cell proliferation, migration and chemosensitivity in glial tumours when overexpressed by the transfection of the MEG3 gene and suppressed by small interference RNA (siRNA)." (PMID 37525401, 2023). "Cell proliferation, cell migration, and drug sensitivity may vary between different glioma subtypes when MEG3 is silenced and overexpressed in glioma cells." (PMID 37525401, 2023). "Based on our hypothesis that cells can be affected in different ways by MEG3 activity, we evaluated how MEG3 gene expression impacts drug sensitivity in glioma cells." (PMID 37525401, 2023). "Subsequently, glioma cells overexpressing MEG3 had less tumorgenicity in xenograft mouse models." (PMID 35860793, 2022). "In addition, another research group revealed that downregulation of MEG3 induced EMT, migration, and invasion of glioma cells, and overexpression of MEG3 induced autophagy in glioma cells." (PMID 36544907, 2022). "LncRNA MEG3 was reported to be involved in cisplatin resistance in glioma cells through autophagy." (PMID 35674307, 2022). "This study was conducted to investigate the impact and mechanisms of lncRNA MEG3 on glioma cells." (PMID 35860793, 2022). "MEG3 could induce G0/G1 cell cycle arrest in glioma and ovarian cancer cells by inactivating the Wnt/β-catenin signaling pathway and upregulating PTEN expression, respectively." (PMID 36551518, 2022). "In glioma cells, LncRNA MEG3 also simultaneously reduced cisplatin-induced autophagy." (PMID 35674307, 2022).
glioma (continued). "MEG3 is known to impair cell proliferation and to promote apoptosis in glioma cells." (PMID 36323673, 2022). "Similar results indicated that MEG3 might be used as a biomarker for glioma prognosis and as a promising immunotherapy biomarker." (PMID 36544907, 2022). "lncRNA MEG3, the first lncRNA confirmed to have a tumor suppressor function, has been found to have an important regulatory function in neurological diseases such as glioma and ischemic stroke." (PMID 35338543, 2022). "The findings would offer new clues to the use of MEG3 as a gene therapeutic agent for glioma." (PMID 35860793, 2022). "Our findings suggest that lncRNA MEG3 may be further explored as a potential new gene therapeutic agent for the treatment of glioma." (PMID 35860793, 2022). "MEG3 was also shown to inhibit proliferation and promote apoptosis in human glioma cell lines." (PMID 35860793, 2022). "LncRNA MEG3 was found to be down-regulated in glioma-resistant cell lines." (PMID 35674307, 2022). "Furthermore, using the PrognoScan database, we observed that MEG3 expression was significantly correlated with the prognosis of a total of nine cancer types, including gliomas." (PMID 34220951, 2021). "Furthermore, MEG3 expression showed strong correlations with multiple immune markers in gliomas, especially in LGG." (PMID 34220951, 2021). "MEG3 reduces the growth of glioma cells by inactivating the PI3K/AKT signaling pathway." (PMID 33692824, 2021). "The current findings suggest that MEG3 expression might serve as a possible prognostic marker and potential immunotherapeutic target for gliomas." (PMID 34220951, 2021). "It was found that MEG3 expression was significantly reduced or completely lost in 25% of neuroblastomas, 81% of hepatocellular cancers, and 82% of gliomas." (PMID 34220951, 2021). "TIMER database was used to evaluate whether the expression of MEG3 in glioma is correlated with immune infiltration." (PMID 34220951, 2021). "Determining treatment response: MEG3 also determined chemoresponse in glioma." (PMID 34322395, 2021). "Taken together, the current findings suggest that the expression of MEG3 might serve as a possible prognostic biomarker and potential immunotherapeutic target for gliomas." (PMID 34220951, 2021). "Univariate analysis of the correlation of MEG3 expression and immune infiltrates with OS in glioma." (PMID 34220951, 2021). "MEG3 can act as a ceRNA for miR-19a, thereby exerting an inhibitory effect on glioma." (PMID 33499813, 2021). "Furthermore, our analyses showed that levels of immune cell infiltration and diverse immune marker sets were correlated with the level of MEG3 expression in gliomas, especially in LGG." (PMID 34220951, 2021). "Taken together, these results were consistent with previous studies that MEG3 might serve as a tumor suppressor in most human cancers, including gliomas." (PMID 34220951, 2021). "For instance, MEG3 impeded cell growth while promoting apoptosis and autophagy in glioma cells." (PMID 33332708, 2021). "We also further analyzed the expression of MEG3 in different grades of gliomas, finding that the expression level of MEG3 in grade 4 was significantly lower than that in other grades of gliomas and normal control, it decreased with the increasing of malignant degree of gliomas." (PMID 34220951, 2021). "have reported over-expression of MEG3 in glioma cells treated with cisplatin." (PMID 34178658, 2021). "Invasion and metastasis: Silencing of MEG3 increased migration and invasion in glioma." (PMID 34322395, 2021). "The observed correlation between MEG3 and the expression of certain immunological marker genes suggests that, in gliomas, MEG3 may interact with infiltrated immune cells within the tumor microenvironment." (PMID 34220951, 2021). "Additionally, the mechanism of another differentially expressed lncRNA MEG3 in glioma clinical prognosis, apoptosis, and mitochondrial function warrants further exploration." (PMID 34777696, 2021).
glioma (continued). "MEG3 downregulation in gliomas was recently found to be due to hypermethylation of its promoter." (PMID 34316694, 2021). "Studies have shown that MEG3 is under-expressed in gliomas, and its over-expression has a significant inhibitory effect on the proliferation and migration of glioma cells, while promoting its apoptosis and autophagy, and inhibiting the PI3K/AKT/mTOR signalling pathway." (PMID 33499813, 2021). "The association between MEG3 expression and immune cell infiltration indirectly indicated that MEG3 may be a useful predictor of glioma patient survival." (PMID 34220951, 2021). "The success of immunotherapies calls for the evaluation of the role of MEG3 in gliomas." (PMID 34220951, 2021). "Similarly, the overexpression of MEG3 downregulates the expression of N-cadherin, Vimentin, and Snail, while silencing MEG3 increases the expression of these markers in glioma cells and cholangiocarcinoma cells." (PMID 34069546, 2021). "However, little was known about the mechanism of lncRNA maternally expressed gene 3 (MEG3) in the development and progression of glioma." (PMID 32420340, 2020). "The proposal of the possible mechanism of the miR-6088/SMARCB axis may contribute to a better understanding of lncRNA MEG3 on glioma cells and facilitate the potential therapy for amelioration of the risk of glioma." (PMID 32420340, 2020). "In the present work, we uncovered that lncRNA MEG3 was obviously downexpressed in glioma cells, and we revealed that lncRNA MEG3 can function as a ceRNA to mediate miR-6088/SMARCB axis and thereby decrease cell migration, proliferation, and EMT in glioma cells." (PMID 32420340, 2020). "As we proved that both MEG3 and SMARCB1 are implicated in glioma cells, no direct interaction is found between MEG3 and SMARCB1." (PMID 32420340, 2020). "lncRNA MEG3, located in the chromosome 14 DLK1-MEG3 imprinting region, were down-regulated in a variety of primary human cancers, including lung cancer, hepatocellular cancer, multiple myeloma, meningioma and glioma." (PMID 31938020, 2020). "A previous report manifested that MEG3 could retard aggressive behaviors, including cell proliferation, migration, and invasion by sponging miR-19a in glioma cells." (PMID 33251130, 2020). "In addition, downregulation of MEG3 was also observed in human glioma cell lines, compared with normal astrocytes." (PMID 32650527, 2020). "Subsequently, lncRNA MEG3 expression was found to be downregulated in glioma tissue cells." (PMID 33329296, 2020). "It was reported that MEG3 could serve as a cancer suppressor and is able to induce the apoptosis of gliomas cells and leukemia cells." (PMID 31660855, 2019). "Zhang’s study showed that MEG3 could reduce gliomas growth, tumor volume and the expression of ki67." (PMID 31488093, 2019). "MEG3 suppresses glioma cell proliferation, migration and invasion by sponging miR-19a." (PMID 29552296, 2018). "In cisplatin-treated glioma cell line, MEG3 expression levels were increased." (PMID 30266744, 2018). "On the contrary, MEG3 expression has been strongly decreased in glioma and its expression decreases with malignancy grade, thus acting as a tumour suppressor and contributing to glioma progression." (PMID 29138748, 2017). "For example, MEG3 expression level is decreased in lung cancer, hepatocellular cancer, prostate cancer, multiple myeloma, meningioma, gastric cancer, and glioma." (PMID 29069869, 2017). "Glioma cell proliferation was inhibited with increased apoptosis when MEG3 was overexpressed." (PMID 26230711, 2015). "The lncRNA MEG3 derived from the DLK1-DIO3 locus possesses tumor suppressor properties in several cancer types, many of which are associated with the nervous system, including pituitary tumors, neuroblastomas, meningiomas, and gliomas." (PMID 25559585, 2015). "For example, MEG3 expression in glioma tissues is decreased compared to adjacent normal tissues." (PMID 24550934, 2014).